MYC (MYC proto-oncogene, bHLH transcription factor)
Diseases named in the same sentence as MYC in open-access papers (continued):
Sharing a sentence is not in itself a finding about the gene and the disease.
tumor (continued). "The possibility to control MYC activation and Rb deletion with two different methods (removal of doxycycline and Cre-mediated recombination, respectively) also allowed us to test the possibility that the order of the mutations in this system may influence tumor development." (PMID 21573126, 2011). "For this purpose we used cell lines with conditional MYCN or c-MYC expression, to screen a library of 80 conventional cytotoxic compounds for their ability to reduce tumor cell viability and/or growth in a MYC dependent way." (PMID 22132187, 2011). "The statistical significance analysis also shows that MYC plays an important role in most of the tumor types analyzed." (PMID 22041030, 2011). "The pro-apoptotic function of overexpressed MYC is often overcome during tumor development by various additional lesions that block apoptosis." (PMID 22132187, 2011). "Zhang and colleagues have recently described that miR-210 influences the hypoxic response in tumor cells through targeting a key transcriptional repressor of the MYC-MAX network." (PMID 21373187, 2011). "Four MYC copies was the most frequent copy number alteration in the tumor biopsies supporting our FISH findings in the ACP03 cells culture at the 85th passage." (PMID 21811552, 2011). "Immunoblot analysis of liver extracts revealed high levels of the MYC protein in all tumor samples compared to controls." (PMID 21573126, 2011). "We selected 5 known tumor-related genes i.e., K-ras, c-MYC, DNMT1, Tpd52, CDKN1b for PCR confirmation." (PMID 22206623, 2011). "In conclusion, overexpression of MYC renders tumor cells particularly sensitive to targeting of certain mechanisms and pathways, including topoisomerases and the mitotic control machinery as shown in this study." (PMID 22132187, 2011). "The control of micro RNAs (miRNAs) by MYC, which can influence the cell cycle, apoptosis, metabolism and tumor metastasis, was described only recently." (PMID 22102868, 2011). "Dlx-5 has been shown to promote tumor cell proliferation by directly binding the MYC promoter and upregulating MYC." (PMID 21917150, 2011). "Both MYC and MYCN oncoproteins act on the mir-9-3 locus and cause activation of miR-9 expression in tumor cells." (PMID 21857930, 2011). "In the validation panel of 295 cases, the amplification of MYC also significantly associated with ECS status, tumor relapse, and survival." (PMID 21853135, 2011). "In the first carcinogenesis model, we observed MYC immunoreactivity, amplification (more than 3 MYC copies) and mRNA overexpression in the tumor biopsies." (PMID 21811552, 2011). "Based on the role of CIP2A in stabilising and up-regulating the MYC oncoprotein, it is likely that MYC is involved in CIP2A-stimulated invasiveness of tumour cells." (PMID 22075943, 2011). "Elevated MYC expression can be found in up to 70% of human tumors, and suppression of MYC is thought to lead to tumor regression." (PMID 22102868, 2011). "Immunohistochemistry, relative quantitation of mRNA MYC expression and MYC gene copy number variation by Taqman and fluorescence in situ hybridization in tumor biopsies of animals included in the first carcinogenesis model on the 9th day of treatments." (PMID 21811552, 2011). "Principal common CNAs were the well known MYC-associated gain and RB1/INTS6-associated loss that occurred in all mouse and human tumor groups, and the AURKA-associated gain occurred in BRCA2-related tumors from both species." (PMID 20735817, 2010). "MYC, BMP2, and FOS show an associative trend when overexpressed, and TNFRSF10A shows a trend in underexpression in the tumor cohort." (PMID 20465837, 2010). "RCA identifies RNA expression changes that strongly support decreased transcriptional activity of MYC in all three xenografts as well as in four sensitive tumor cell lines in culture." (PMID 20604938, 2010).
tumor (continued). "Our data indicate that amplification of the MYC locus and loss of the RB/INTS6 locus occurs in all mouse and human tumor groups, and that AURKA amplification occurs in mouse and human BRCA2-mutated tumors." (PMID 20735817, 2010). "This is consistent with the observations that inactivation of ATM diminishes MYC-induced apoptosis and augments MYC-driven tumor development." (PMID 20111719, 2010). "Surprisingly in case of K-Ras mutations, four out of the five cases of c-MYC tumor derived metastases that could be examined in this way were negative for the mutation as was the one case of a compound mouse that had a K-Ras exon 1 mutation in the primary tumor and metastasis to lymph nodes." (PMID 19551151, 2009). "c-MYC alone induced frank tumor growth only after long latency at which time secondary mutations in K-Ras or LKB1 were detected reminiscent of human NSCLC." (PMID 19551151, 2009). "This is most likely due to increased cellular proliferation in tumor cells, as E2F is important in cell proliferation control and MYC is both a p21-repressor and inducer of cyclin D2 and cyclin-dependent kinase binding protein CksHs2." (PMID 19798449, 2009). "Gata6 expression gradually decreased as a function of age in SpC-c-MYC single transgenic and compound mice in primary tumor and liver metastasis." (PMID 19551151, 2009). "It has been shown that polypurine oligonucleotides can form antiparallel triplexes with G-rich TTSs in promoter regions of c-myb, MYC, Ki-ras (and some other oncogenes) and reduce both the proliferation and colony formation in tumor cells." (PMID 19958507, 2009). "As the kinetics of tumor development was delayed in SpC-c-MYC mice as compared to SpC-C-RAF BxB or compound mice and the number of late tumors per lung was lower we searched for secondary mutations." (PMID 19551151, 2009). "The incidence and rate of local tumor growth was increased by MYC expression to such a degree that animals had to be sacrificed after six weeks." (PMID 19551151, 2009). "A major difference however was the high level of C-RAF expression from the transgene which mediates rescue of cryptic c-MYC transformants from apoptosis leading to expansion of early tumor foci." (PMID 19551151, 2009). "Instead VEGF expression was detected in tumor cells of lung tumors from SpC-c-MYC single transgenic or compound mice." (PMID 19551151, 2009). "Many strategies are currently under development to target c-MYC in tumor cells, including inhibitors that block c-MYC expression, such as antisense oligonucleotides and small interfering RNA (siRNA)." (PMID 19134217, 2009). "In a recent study it was shown that hypomethylation of the LINE 1 retrotransposon, as well as amplification of MYC can be used to predict tumour stage in prostate cancer." (PMID 19506729, 2008). "Their roles in terminal differentiation and growth arrest, and their ability to block MYC-induced transformation have led to them being postulated as tumour suppressor genes." (PMID 18493233, 2008). "In all three types of mutants, when MYC expression becomes deregulated such that MYC is over expressed, the transformed B cell proliferates and starts to form a tumour." (PMID 18578571, 2008). "The tumors that arose in the MMTV-rtTA/TRE-MYC/BCRHEL/sHEL mice displayed sustained dependence upon both the activity of the MYC transgene and the stimulus to tumor cells provided by a cognate autoantigen." (PMID 18578569, 2008). "To verify these observations in vivo, we isolated tumor cells from Eμ-MYC/BCRHEL mice, and transduced them." (PMID 18578569, 2008). "Activated tumor cells stained intensely for MYC protein by IHC analysis and were TTF-1 positive as expected (data not shown)." (PMID 18461184, 2008). "It is important to note that localized-NA tumors also express MYCN as well as c-MYC and it is likely that they are active because these tumors frequently show high tumor cell proliferation indices." (PMID 18851746, 2008).
tumor (continued). "We conclude that a constitutive BCR can cooperate with MYC in the genesis of BCLs and can elicit a distinctive phenotype in the tumor cells." (PMID 18578569, 2008). "Oncogene activation by genomic amplification, which usually occurs during tumour progression, is seen in the members of different oncogene families including MYC, CCND, EGFR, and FOS." (PMID 19506729, 2008). "Transduction was performed with tumor cells isolated from either Eμ-MYC/BCRHEL mice or Eμ-MYC/BCRHEL/sHEL mice." (PMID 18578569, 2008). "In contrast to the preceding findings, tumor cells obtained from Eμ-MYC/BCRHEL/sHEL mice or MMTV-rtTA/TRE-MYC/BCRHEL/sHEL mice would grow into lethal tumors when transplanted into recipient mice in the absence of HEL antigen." (PMID 18578569, 2008). "It is not clear why EμMYC/BCRHEL and EμMYC/BCRHEL/sHEL or MMTV-rtTA/TRE-MYC/BCRHEL/sHEL tumours respond differently to immunosuppressants." (PMID 18578571, 2008). "The ability of MYC and K-rasG12D to cooperate for tumorigenesis and the ability of the inactivation of these oncogenes to result in tumor regression depended upon the specific tissue context." (PMID 18461184, 2008). "Evidence of tumor in Eμ-MYC/BCRHEL mice appeared first in the spleen at about 18 wk of age, then in lymph nodes and the bone marrow." (PMID 18578569, 2008). "The surface phenotype of MMTV-rtTA/TRE-MYC/BCRHEL/sHEL tumor cells also resembled that of Eμ-MYC/BCRHEL/sHEL tumors." (PMID 18578569, 2008). "We were surprised to find that CM tumors were independent of MYC, since a multitude of previous studies have demonstrated that MYC-induced tumors exhibit complete tumor regression upon MYC inactivation." (PMID 18461184, 2008). "Previously, cyclin D1-regulated genes from the Lamb profile dataset and Myc-regulated genes from the Coller dataset were each shown to be coordinately expressed with CCND1 and MYC mRNA expression, respectively, in various tumor datasets." (PMID 18350153, 2008). "In contrast, the sixth candidate, MYC, was not only found to be differentially expressed in tumour vs BPH, but also correlated with both Gleason score and pT-stage." (PMID 17146477, 2007). "Although eight of those normal samples expressed c-MYC mRNA, the expression level was much lower compared to that in their paired tumour tissues." (PMID 16670719, 2006). "c-MYC mRNA was expressed in all 29 tumours examined, whereas lower or comparable levels of c-MYC expression was only observed in 8/29 normal renal samples." (PMID 16670719, 2006). "Overexpression of MYC and HGFR/MET is implicated in the aetiology of a variety of tumours and would serve as an important therapeutic target." (PMID 16919171, 2006). "The increased levels of MYC expression we observed in tumors likely reflect that the proliferating tumor cells express more abundant levels of the MYC transgene than normal hepatocytes." (PMID 15455033, 2004). "In this regard, we have shown that upon inactivating MYC, tumor cells differentiated, and upon MYC reactivation in this new differentiative state, cells underwent apoptosis." (PMID 15455033, 2004). "Mice that overexpressed MYC during embryonic development of the liver succumbed to neoplasia within 10 d of birth." (PMID 15455033, 2004). "In embryonic and neonatal mice, MYC overexpression in the liver induced marked cell proliferation and immediate onset of neoplasia." (PMID 15455033, 2004). "MYC regulates broad transcriptional networks controlling proliferation, metabolism, angiogenesis, and cell survival, while also orchestrating profound remodeling of the tumor microenvironment (TME)." (PMID 41659859, 2026). "Interestingly, oncogene expression in the tumour-primed population (K14-BRAFV600E-tdRFP) exhibited strong pSTAT3 and MYC activation from day 8 in hyperplastic lesions, which persisted later in the tumours." (PMID 41507151, 2026).
tumor (continued). "In humans, subtypes of the Let-7 family (a-g and i) share a high degree of sequence similarity and are primarily known as tumor suppressors that downregulate the expression of target genes such as MYC, KRAS, and LIN-28 effecting cell differentiation, growth and survival." (PMID 41510819, 2026). "Overall, these results reveal shared molecular and transcriptional hallmarks of epidermal transformation that rely on MYC and pSTAT3 activation for transformation and are independent of the cell of origin, tumour latency, or oncogenic driver mutations." (PMID 41507151, 2026). "Understanding this mechanism may suggest methods to inhibit MYC-driven topoisomerase activation, targeting tumor-specific transcription." (PMID 41663397, 2026). "Given MYC's ability to reprogram cancer metabolism and the liver's role in coordinating systemic metabolism, we hypothesized that MYC induces metabolic dependencies that could be targeted to attenuate tumor growth." (PMID 41849351, 2026). "Finally, treating a MYC-driven liver tumor model with L-cycloserine diminished the frequency of mouse tumor formation and attenuated the growth of established human liver tumors." (PMID 41849351, 2026). "Overall survival and tumor-specific survival correlated negatively with the MYC score." (PMID 42032556, 2026). "Additionally, SNF5/BAF47 (it is encoded by the SMARCB1) has traditionally been regarded as a tumour suppressor protein capable of exerting tumour suppression by inhibiting MYC activity." (PMID 39779467, 2025). "The high TELscore group exhibited significantly elevated mutation enrichment in several key oncogenic pathways, including HIPPO, MYC, NOTCH, RTK-RAS, TGF-β, and WNT, all of which are closely associated with tumor cell proliferation, invasion, and immune regulation." (PMID 40492114, 2025). "Similarly, MYC-mediated SDHA acetylation plays a crucial role in tumor cell growth via epigenetic regulation." (PMID 40186663, 2025). "Normally, FBXW7 targets MYC for proteasomal degradation, acting as a tumor suppressor." (PMID 40076599, 2025). "Notably, MYC-mediated immune evasion is characterized by tumor type-specific mechanistic heterogeneity, necessitating tailored combinatorial immunotherapies that target distinct immune suppressive pathways." (PMID 40732268, 2025). "Indeed, our results showed that combination of MYC inhibition with anti-VEGF inhibitors in TECs exhibited enhanced efficacy in suppressing tumor growth." (PMID 40303332, 2025). "tumor cells are unable to synthesize arginine due to argininosuccinate synthetase 1 (ASS1) deficiency, and instead upregulate insulin-like growth factor 1 (IGF-1R) and enhance ASS1 transcription via c-MYC for arginine metabolic reprogramming." (PMID 39925801, 2025). "Theoretically, c-MYC inhibitors could have complex effects on the immune response, influencing both tumor cells and immune cells." (PMID 40333779, 2025). "We investigated whether inhibition of the tumor and downregulation of the c-MYC and PD-L1 expression led to the inhibition of metastasis to the lungs, liver, and pancreas." (PMID 40949131, 2025). "Taken together, targeting MYC significantly enhances macrophage-mediated tumor cell destruction." (PMID 40732268, 2025).
tumor (continued). "In addition, our data challenge the cutoffs used for a tumour to be called MYC/MYCN-amplified by FISH, as even the smallest MYC subclones, which initially have low abundance, have the potential to expand into the dominant clone during relapse." (PMID 40335697, 2025). "Conversely, in a microenvironment characterized by heightened immune pressure, PRMT3 may pivot toward enhancing immune evasion strategies through c-MYC stabilization or other tumor-promoting pathways." (PMID 41583428, 2025). "Complex 2 significantly decreased the expression of the c-MYC gene and extracellular-matrix-related genes and upregulated thegenes in the VEGF signaling pathway in tumor tissues, which are allclosely associated with BRD4 modulation, ultimately resulting in reducedtumor volume in mouse models." (PMID 41152016, 2025). "Additionally, studies have shown that IGF-1 overexpression can enhance MYC expression, and MYC also can promote tumor cell growth through paracrine signaling mediated by the IGF-1/IGF-1R axis." (PMID 40160318, 2025). "In cancers where MYC plays a critical role in tumor growth and chemoresistance, combining PA2G4 inhibition with chemotherapy could provide a more effective strategy for overcoming drug resistance and improving patient outcomes." (PMID 41002386, 2025). "Interestingly, research has shown that silencing or inhibiting c-MYC expression leads to tumor regression and TME remodeling, restoring immune responses." (PMID 40333779, 2025). "The increase of c-MYC in malignant breast cells drives faster tumor expansion by increasing the viability of cancer stem cells and initiating a metabolic change that supports tumor growth." (PMID 40711670, 2025). "Inhibition of glutaminase in MYC-driven RCC models has slowed tumor progression, indicating that targeting glutamine metabolism could be a viable therapeutic strategy for MYC-driven cancers." (PMID 40253354, 2025). "Peptide‐mediated inhibition of the PLXDC2‐cortactin binding led to a reduction in the mRNA levels of the tumor‐related genes MYC (p < 0.05) and POU5C1, and the proliferation‐related gene MKI67 (p < 0.05), while the mRNA levels of PLXDC2 and cortactin remained unchanged." (PMID 41365610, 2025). "In SCLC, MYC can drive NE phenotypes, but under certain contexts, it might also promote squamous characteristics, potentially influencing tumor heterogeneity." (PMID 41023204, 2025). "Similarly, other studies confirmed the tumour-suppressive function of miR-184 both in vitro and in vivo, with c-MYC identified as a recurrent target and potential therapeutic focus." (PMID 41379397, 2025). "As cargos, our results showed that the delivery of the MYC siRNA notably downregulated the MYC expression in TECs, accompanied by tumor vessel normalization in both RBPj∆E and Ctrl mice, confirming that MYC is an authentic downstream target for Notch activation to repress TEC proliferation." (PMID 40303332, 2025). "This could be a method by which HSF1 and MYC affect metabolism to support their functions in tumor cells." (PMID 39831777, 2025). "HCCOs derived from end-stage tumours of cohort 5 (BM) mice expressed β-catenin, its downstream target GS and retained MYC overexpression as well as markers of proliferation (Ki-67) and differentiation (HNF4a), features that are shared with the corresponding primary tumour." (PMID 39972137, 2025).